TLR4 (toll like receptor 4)
Diseases named in the same sentence as TLR4 in open-access papers (continued):
Sharing a sentence is not in itself a finding about the gene and the disease.
Acute hepatitis (6 papers, 2015 to 2026). Acute hepatic injury resulting from inflammation typically accompanied by increased serum alanine transaminase activity. "In conclusion, this study identifies hepatocyte-derived BDNF as an endogenous antagonist of TLR4 and a critical immune checkpoint in acute hepatitis." (PMID 41881032, 2026). "In summary, CA-NPs exhibit significant hepatoprotective effects in the D-Gal and radiation-induced acute hepatitis rat model by inhibiting the MyD88/TLR4 pathway, providing experimental evidence for their clinical application in treating acute hepatitis." (PMID 40872532, 2025).
aortic valve stenosis (6 papers, 2015 to 2024). Aortic valve stenosis (AVS) is a condition characterized by narrowing of the heart's aortic valve opening. "Moreover, in the interstitial cells of human aortic valve stenosis, Notch1 enhances the inflammatory response and promotes the osteogenic response under the stimulation of TLR4 by regulating the activation of NF-κB." (PMID 35891967, 2022). "We suggest that TLR4 inhibition by antisense strategies or pharmacological approaches may emerge as an alternative method in the treatment of coronary stenosis to prevent the development of contractile dysfunction and HF." (PMID 26030867, 2015). "This study investigated the expression of miR-146a and of its targets, TLR4 and IRAK1, in valvular tissue obtained from the patients with aortic valve stenosis." (PMID 31294031, 2019). "In the present study, we have investigated the expression of miR-146a and its targets, TLR4 a IRAK1, in aortic valve stenosis." (PMID 31294031, 2019).
arteriosclerosis (6 papers, 2013 to 2022). A vascular disorder characterized by thickening and hardening of the walls of the arteries. "In conclusion, AS-6 is a promising inhibitor of chronic inflammation of diseases such as arteriosclerosis and plaque instability involving TLR4." (PMID 31001118, 2019). "Taken together, these results suggest that TLR4 deficiency protects the renal vasculature from Ang-II induced remodeling whereas mice with normal TLR4 develop vascular dysfunction suggestive of arteriosclerosis in the kidney." (PMID 28743964, 2017). "ApoE also affects the immune response, and in mice, ApoE KO increased the expression of Toll-like receptor 4 (TLR4) and LOX-1, suggesting the formation of foam cells and promoting the onset of arteriosclerosis." (PMID 35955522, 2022). "We measured expression of TLR4, TIRAP, MyD88, TRAF6, p38, NEMO, and IRF5 to test the anti-arteriosclerosis effect of corilagin." (PMID 32849545, 2020). "Toll-like receptor 4 (TLR4) and matrix metalloproteinase-9 (MMP-9) are known to play important roles in inflammatory diseases such as arteriosclerosis and plaque instability." (PMID 31001118, 2019). "As a proinflammatory factor, toll-like receptor 4 (TLR4) upregulates MMP9 expression and mediates inflammatory responses and also contributes to arteriosclerosis." (PMID 23844137, 2013).
Atrophy (6 papers, 2015 to 2026). Any weakening or degeneration, especially through lack of use. "Although the mechanisms regulating muscle atrophy are complex, activation of TLR4 signaling has been considered to be associated with inactivity‐induced muscle atrophy." (PMID 28432254, 2017). "The TLR4 polymorphisms did not correlate with the Sydney system based variables of chronic or active gastritis, atrophy, intestinal metaplasia or H. pylori score." (PMID 26161647, 2015).
bacterial meningitis (6 papers, 2012 to 2025). Inflammation of the membranes surrounding the brain and spinal cord due to a bacterial infection. "Our findings provide valuable insights for targeting TLR4 in the prevention and treatment of bacterial meningitis and neuroinflammation." (PMID 40821830, 2025). "In this study, only one SNP of TLR4 and TLR9 was tested, and the possible effects of the other SNPs in the two genes on the susceptibility to and outcome of bacterial meningitis should also be kept in mind." (PMID 32967147, 2020). "While TLR4 has been traditionally viewed as a critical pattern recognition receptor for bacterial LPS detection and innate immune activation, our findings reveal its complex involvement in balancing protective and destructive host responses during bacterial meningitis." (PMID 40821830, 2025). "Eleven SNPs in seven genes (TLR2, TLR4, TLR9, NOD1, NOD2, CASP1, and TRAIL) were genotyped in 393 survivors of childhood bacterial meningitis (BM) (327 MM patients and 66 PM patients)." (PMID 22662111, 2012). "Among TLRs, TLR2, TLR4, TLR9 are involved in the pathogenesis of bacterial meningitis." (PMID 33808027, 2021).
C. perfringens infection (6 papers, 2019 to 2025). "Furthermore, DNA microarray analysis revealed that the mutation in TLR4 partially affects host gene expression during C. perfringens infection." (PMID 33763386, 2021). "At present, only a few studies have demonstrated that toll-like receptor 4 accelerates granulopoiesis and enhances host defense against C. perfringens infection." (PMID 38622656, 2024). "It was previously demonstrated that C. perfringens θ-toxin is a TLR4 agonist, but the role of TLR4 in C. perfringens infection is unclear." (PMID 33763386, 2021). "G-CSF was greatly increased in C. perfringens-infected muscle from C3H/HeN mice, while the increase was limited in that from C3H/HeJ mice, suggesting that TLR4 plays a role in the regulation of granulopoiesis during C. perfringens infection." (PMID 33763386, 2021). "Together, our results indicate that TLR4 signaling plays an important role in the regulation of G-CSF-mediating granulopoiesis during C. perfringens infection, and this mechanism probably contributes to the replenishment of neutrophils and the elimination of bacteria." (PMID 33763386, 2021). "The results suggest that TLR2 plays a complementary role to TLR4 during C. perfringens infection." (PMID 33763386, 2021). "Together, it should be meaningful to speculate the role of α-toxin in TLR4-mediated inflammatory response in C. perfringens infection." (PMID 30729183, 2019). "Thus the activation of not only TLR2 but also TLR4 by α-toxin should be important to understand clinical features of C. perfringens infection." (PMID 30729183, 2019). "However, the role of TLR4 in C. perfringens infection is unclear." (PMID 33763386, 2021). "Docking was performed against TLR1/TLR2 and TLR4/MD2, as they have been widely reported to be important in the innate defense against C. perfringens infection in chickens and mice, although little is known in humans." (PMID 36110855, 2022). "In the previous report, it was unclear whether it is meaningful to speculate on the role of α-toxin in the TLR4-mediated inflammatory response in C. perfringens infection, because C. perfringens do not contain LPS." (PMID 33763386, 2021). "In addition, a study on the host immune response induced by C. perfringens infection in pig ileum indicated that, unlike the jejunum, C. perfringens was able to activate the TLR4/MyD88/NF-κB signalling pathway in the ileum, activating downstream immune-related cytokines." (PMID 40869997, 2025).
cardiac arrest (6 papers, 2016 to 2025). Cessation of breathing and/or cardiac function. "Suppressing the TLR4 axis using a targeted inhibitor can prevent neuronal loss, and suppress NF‐κB p65 activation following cardiac arrest and cardiopulmonary resuscitation." (PMID 37132060, 2023). "For example, Xu and colleagues conducted potassium-induced cardiac arrest in TLR4 mutant mice (C3H/HeJ) for 3 min followed by CPR." (PMID 31369614, 2019). "On a functional level, we observed a pronounced and sustained decrease in inflammatory cytokine release after TLR2 and TLR4 activation in patients after cardiac arrest ex vivo." (PMID 27260481, 2016). "FK866, a nicotinamide phosphoribosyltransferase inhibitor, which binds to Toll-like receptor 4 (TLR4) and activates the inflammasome, was evaluated to determine its efficacy against brain reperfusion damage in rats subjected to cardiac arrest/cardiopulmonary resuscitation." (PMID 34832998, 2021). "Whole blood samples taken from patients after cardiac arrest had markedly impaired synthesis of IL-1β in response to stimulation with the TLR4 agonist LPS (CAD 327.0 ± 291.3; CPR t1 31.3 ± 49.7; CPR t2 28.0 ± 35.6; CPR t3 33.5 ± 60.6 ((pg/ml)/white blood cell (WBC) count))." (PMID 27260481, 2016). "In this study, we provide evidence for the activation of TLR2 and TLR4 in immediate survivors of cardiac arrest and describe the involvement of the NLRP3 inflammasome in the modulation of the subsequent systemic inflammatory response to global IRI caused by temporary circulatory arrest." (PMID 27260481, 2016). "Monocyte TLR2, TLR4, IRAK3, IRAK4, NLRP3, PYCARD and IL1B were initially upregulated in patients following cardiac arrest." (PMID 27260481, 2016). "In analysis of time-dependent expression of monocyte mRNA in patients after cardiac arrest, significantly higher levels of TLR2, TLR4, IRAK3, NLRP3, and IL1B were observed in patients in the early hours after ROSC compared to the later phase." (PMID 27260481, 2016). "Serum lactate levels at the time of blood sampling were significantly positively correlated with TLR2 (rs 0.570; p = 0.001), TLR4 (rs 0.369; p = 0.045), IRAK3 (rs 0.569; p = 0.001), and IRAK4 (rs 0.413; p = 0.029) monocyte mRNA levels in the early phase after cardiac arrest." (PMID 27260481, 2016).
Chagas disease (6 papers, 2010 to 2022). A parasitic infection caused by Trypanosoma cruzi. "In response to Chagas disease, it was able to bind to TLR4, MHC-I, and MHC-II and induce a strong immune response in computational analysis." (PMID 36298534, 2022). "On the other hand, patients with different clinical manifestations of Chagas disease showed similar mRNA expression levels of TLR1, TLR3, TLR4, TLR5, TLR6, TLR7 and TLR9." (PMID 30044791, 2018). "Patients with different clinical manifestations of Chagas disease showed similar expression of TLR1, TLR3, TLR4, TLR5, TLR6, TLR7 and TLR9 mRNA." (PMID 30044791, 2018). "TLRs are involved in both protection against and the pathology of Chagas disease, and among these receptors, it is estimated that TLR2, TLR4, and TLR9 are the most important." (PMID 25371910, 2014). "Recently, we reported that TLR2, TLR4 and TLR9 are differentially modulated in injured livers from BALB/c and C57BL/6 (B6) mice during Trypanosoma cruzi infection." (PMID 21072226, 2010).
childhood asthma (6 papers, 2014 to 2024). "We aimed to explore the role of TLR4 (rs4986790) polymorphism in the nasopharyngeal (NP) bacterial colonization and its consequent impact on the development of childhood asthma." (PMID 32650475, 2020). "TLR4 rs10759932 SNP has been reported to be associated with childhood asthma and psoriasis vulgaris." (PMID 28912808, 2017). "Elevated levels of seven proteins (TLR4, UBP25, CBR1, Rac GTPase‐activating protein 1 [RGAP1], IL‐21, MICB, and PDE4D) and decreased levels of three proteins (GSTO1, LIRB4 and PIGF) were associated with an increased risk of childhood asthma." (PMID 38730525, 2024). "Based on the genetic data of 4419 (of 4489) plasma proteins from UK Biobank, our study presents compelling evidence linking 10 plasma proteins (GSTO1, LIRB4, PIGF, IL‐21, MICB, PDE4D, RGAP1, TLR4, UBP25 and CBR1) to childhood asthma." (PMID 38730525, 2024).
chronic hepatitis (6 papers, 2012 to 2023). An active inflammatory process affecting the liver for more than six months. "LPS, a trigger for hepatic inflammation in ALD, translocates to liver via portal vein and binds to TLR-4 of antigen presenting cells (APCs) to induce inflammatory immune response and finally cause chronic hepatitis." (PMID 28228158, 2017). "Several other studies also found increased expression of TLR2 and TLR4 mRNA in chronic hepatitis patients compared to controls." (PMID 35628287, 2022). "However, TLR4 mRNA expression was downregulated in cirrhotic patients when compared to chronic hepatitis patients." (PMID 35628287, 2022). "TLR4 is an important member of the TLR family and a receptor for LPS, has been found in the portal vein of chronic hepatitis patients and expressed in HSCs and KC cells too." (PMID 22927965, 2012).
contact dermatitis (6 papers, 2017 to 2024). An inflammatory skin condition caused by direct contact between the skin and either an irritating substance or an allergen. "Consequently, the inhibition of IL-8 release from Caco-2 cells and the UC prevention and improving effect in mice observed in the present study are suggested to be caused by the TLR-4 signaling pathway, as previously predicted in contact dermatitis model mice." (PMID 34835369, 2021). "Other studies have shown that these cytokines are produced by macrophages and effector T cells, and that TLR4 increases the sensitivity of contact dermatitis." (PMID 31959814, 2020). "In the CHS model the loss of TLR2 and TLR4 leads to resistance against contact dermatitis, i.e. either the oxidative stress and the in flammasome pathways alone are not sufficient to permit contact dermatitis or these pathways are not efficiently activated without these TLR." (PMID 30402600, 2017). "Furthermore, mRNA levels of contact dermatitis-related cytokines were measured by real-time polymerase chain reaction, and effects of TAK-242, a toll-like receptor 4 (TLR4) inhibitor, on the contact hypersensitivity (CHS) response were evaluated." (PMID 31959814, 2020). "Studies in the mouse model of contact dermatitis, the contact hypersensitivity (CHS) model, showed that the simultaneous absence of TLR2 and TLR4 leads to resistance against potent contact allergens like TNCB and oxazolone." (PMID 30402600, 2017).
Cryptosporidium infection (6 papers, 2013 to 2025). "To test C. parvum-induced exosome release in vivo, we applied a mouse model of biliary cryptosporidiosis through gallbladder injection of C. parvum oocysts into wild-type and TLR4-deficient mice." (PMID 23592986, 2013). "This research sheds light on potential therapeutic strategies that target the TLR4/STAT1 pathway to combat Cryptosporidium infections effectively." (PMID 39902829, 2025). "This is the first study to indicate an association between TLR4 and TIRAP polymorphisms with cryptosporidiosis." (PMID 34583337, 2021). "For example, intestinal epithelial cells increased the release of antimicrobial peptide-containing exosomes in response to Cryptosporidium infection, which is driven by enhanced toll-like receptor 4 signaling following recognition of the protozoan parasite." (PMID 30678719, 2019). "Signaling TLR3 in combination with TLR5, TLR4 and TLR9 independently influence Cryptosporidium infection outcomes." (PMID 27467505, 2016).
Encephalopathy (6 papers, 2014 to 2025). Encephalopathy is a term that means brain disease, damage, or malfunction. "Toll-like receptor 4 (TLR4) is a major mediator of inflammation and TLR4 has been implicated in the pathogenesis of post-resuscitation encephalopathy." (PMID 31369614, 2019). "On the other hand, the occurrence and development of encephalopathies are closely related to TLR4‐induced activation of downstream pathways and autophagy in cells, indicating that TLR4 is crucial in RSV infection‐induced encephalopathies." (PMID 38683122, 2024). "Results of the present study demonstrated a novel finding regarding the crucial role of Plexin-A1 expressed in mouse microglia, i.e., its activity in enhancing microglial TLR4-mediated signaling in the development of LPS-induced encephalopathy in mice." (PMID 24604454, 2014). "In the current study, we hypothesised that microglial NLRP3 inflammasome would be activated by RSV via TLR4 and regulate neuroinflammation, a potential mechanism associated with RSV‐associated encephalopathy." (PMID 38683122, 2024). "The data suggest that a crosstalk between Plexin-A1 and the TLR4 pathway synergistically enhances the activation of microglia, and thus Plexin-A1-mediated signaling in microglia has an essential role in the development of LPS-induced encephalopathy." (PMID 24604454, 2014).
Epileptic Seizure (6 papers, 2016 to 2024). "Experimental KA injection successfully initiated an epileptic seizure accompanied by increased expression of TLR4 in the prefrontal cortex, hippocampus, and somatosensory cortex." (PMID 29682548, 2018). "Seizure-induced TLR4/MYD88 signaling plays a critical role in activating microglia and triggering neuron apoptosis." (PMID 27193049, 2016).
esophageal adenocarcinoma (6 papers, 2016 to 2025). A malignant tumor with glandular differentiation arising predominantly from Barrett mucosa in the lower third of the esophagus. "TLR4 expression has been associated with advanced stage and poor prognosis in esophageal adenocarcinoma." (PMID 38709790, 2024). "Increased TLR4 expression associates with advanced stage and poor prognosis in esophageal adenocarcinoma." (PMID 27008696, 2016). "Supporting role of TLR4 activation in pathogenesis of esophageal inflammation and carcinoma, TLR4 activation has been shown to induce Interleukin-8 and NF-kB in esophageal epithelial cells and, more pronouncedly so, in Barrett's esophagus." (PMID 27008696, 2016). "Interestingly, TLR1 (14%; 14/99) and TLR4 (33%; 33/99) showed nuclear staining in esophageal adenocarcinoma." (PMID 27008696, 2016). "TLR4 activation also increased cyclo-oxygenase 2 expression in Barrett's esophagus." (PMID 27008696, 2016). "Although proportion of epithelial cell nuclei with TLR1 and TLR4 expression decreased towards malignancy, the presence of nuclear staining for both TLR1 in (12%) and TLR4 (33%) was common in esophageal adenocarcinomas." (PMID 27008696, 2016).
Heat Stroke (6 papers, 2013 to 2025). A condition caused by the failure of body to dissipate heat in an excessively hot environment or during PHYSICAL EXERTION in a hot environment. "Additionally, TLR4 mitigates heat stroke-induced myocardial injury by suppressing inflammation and ferroptosis." (PMID 40920657, 2025). "In this direction, the work recently published showing increased mortality of TLR4 KO mice under heat stroke suggests that LPS might not play a significant pathogenic role." (PMID 24039931, 2013).
helminth infection (6 papers, 2008 to 2022). "During helminth infection, TLR4 activation induced eosinophil infiltration and increased secretion of mucosal secretory immunoglobulin A (SIgA) antibodies in the infected area, facilitating worm expulsion." (PMID 36238295, 2022). "Increased TLR2 and TLR4 expression in circulating B-cells during helminth infection has already been demonstrated, reflecting systemic exposure to the microbial ligands." (PMID 34784389, 2021). "Cytokine ELISA data showed that helminth infection significantly inhibited LPS-, but not IL-1β-, induced TNF-α and IL-6 production, suggesting that helminth infection specifically inhibits the TLR4 signaling pathway." (PMID 25010669, 2014). "Our data demonstrate a critical role for the MyD88 signaling pathway in host survival during helminth and enteric bacterial co-infection, and also suggest that helminth infection impairs MyD88-independent responses activated by TLR4." (PMID 25010669, 2014). "The expression of both TLR2 and TLR4 genes was lower in children with a helminth infection; the effect being more prominent for TLR2." (PMID 18414649, 2008). "In summary, we provide here the first investigation of gene networks associated with TLR3/TLR4 signaling/cascade within PBMC during F. hepatica infection, which provides useful information for further investigating the roles of TLR3/TLR4 in single cell types, during helminth infection." (PMID 28487699, 2017).